LINC01235 (long independently transcribed non-coding RNA 1235)
Synonyms: FLJ41200
Gene: Long non-coding RNA gene on chromosome 9 (13,406,323 to 13,488,125, reverse strand). Ensembl gene ENSG00000270547.
Diseases named in the same sentence as LINC01235 in open-access papers:
LINC01235 is named in the same sentence as 3 diseases in open-access papers, as found by Europe PMC text mining. Sharing a sentence is not in itself a finding about the gene and the disease. The quoted sentences say what the papers report.
breast carcinoma (2 papers, 2020 to 2023). "LINC01235 upregulation in breast cancer may represent a more aggressive phenotype." (PMID 33206629, 2020).
tumor (2 papers, 2021 to 2024). "Previous studies suggest that LINC01235 is a long-stranded non-coding RNA, located on chromosome 9 p23, which has a characteristic expression pattern because of its inconsistent expression in different tumor tissues." (PMID 34490040, 2021).
LINC01235 also shares sentences with these, for which no sentence is quoted: gastric cancer (1 paper).